APLN (apelin)
Diseases named in the same sentence as APLN in open-access papers (continued):
Sharing a sentence is not in itself a finding about the gene and the disease.
sarcopenia (31 papers, 2018 to 2026). Progressive decline in muscle mass due to aging which results in decreased functional capacity of muscles. "Some scholars have suggested reasons from the perspective of mechanisms that sarcopenia can reduce muscle mass and strength, causing an imbalance in myokine secretion, including inflammatory cytokines, apelin, brain-derived neurotrophic factor, and chemokines." (PMID 40309867, 2025). "The association between circulating apelin levels and muscle phenotypes required for diagnosing sarcopenia was examined using linear regression analysis." (PMID 39787988, 2025). "Differences in serum apelin levels according to the presence of sarcopenia and associated parameters were analyzed using ANCOVA." (PMID 39787988, 2025). "This decline has been linked to sarcopenia, particularly in older men, where lower apelin levels correlate with diminished handgrip strength." (PMID 41441428, 2025). "After observing that reduced apelin levels were specifically associated with sarcopenia in an elderly population, the protective role of apelin in age-associated skeletal muscle atrophy was deemed a promising research avenue." (PMID 38806473, 2024). "The production of apelin, induced by muscle contraction, decreases in an age-dependent manner; thus, apelin is positively associated with the beneficial effects of exercise and can reverse age-associated sarcopenia in older persons." (PMID 37654901, 2023). "Apelin reverses age-associated sarcopenia and apelin treatment increases muscle mass in aged wild-type and Apln−/− mice, a function that is linked to fiber hypertrophy." (PMID 34465345, 2021). "Apelin was significantly associated with the presence of sarcopenia with an OR of 0.254 (95%CI: 0.083–0.778)." (PMID 33743591, 2021). "Apelin reverses age-associated sarcopenia and the interaction between apelin and APJ has therapeutic effects in renal fibrosis, cardiac fibrosis, and pulmonary fibrosis." (PMID 34465345, 2021). "The cutoff point of apelin was negatively associated with the presence of sarcopenia with an OR of 0.254 (95%CI: 0.083–0.778)." (PMID 33743591, 2021). "We found that HtrA1 was associated with decreased presence of sarcopenia in older men and apelin is significantly associated with reduced occurrence of sarcopenia, in women." (PMID 33743591, 2021). "In the present study, we found that HtrA1 and apelin were significantly associated with sarcopenia and provide a potential approach in molecular diagnosis of in older adult population." (PMID 33743591, 2021). "Apelin and HtrA1 were inversely associated with the presence of sarcopenia with an OR of 0.543 (95%CI: 0.397–0.743) and 0.003 (95%CI: 0.001–0.890) after full adjustment." (PMID 33743591, 2021). "Apelin has been recently proposed to be an anti-aging peptide, which in mice extends the healthy life span and prevents sarcopenia, an aging-associated muscle weakness." (PMID 30634441, 2019). "Loss of apelin signaling can lead to premature cardiac aging and age-related sarcopenia." (PMID 40072060, 2025). "Moreover, apelin-deficient mice exhibit accelerated aging phenotypes, including the premature onset of sarcopenia." (PMID 39787988, 2025). "Their findings establish a positive feedback loop between physical activity, apelin, and muscle function, suggesting that apelin could serve as an early diagnostic marker for sarcopenia." (PMID 39683426, 2024). "Loss of apelin signaling results in premature cardiac aging and sarcopenia." (PMID 37175901, 2023). "In addition, exercise-induced apelin secretion reverses age-related muscle loss in people with sarcopenia and enhances mitochondrial biogenesis and protein synthesis of muscle fibers." (PMID 35250869, 2022). "Importantly, apelin-deficient mice exhibited accelerated the onset of sarcopenia and senescence, whereas apelin treatment in aged mice enhanced muscle strength and physical activity and rejuvenated behavioral and circadian phenotypes." (PMID 33087053, 2020).
sarcopenia (continued). "Preclinical studies demonstrate that apelin reverse sarcopenia through enhancing muscle mass, fiber hypertrophy, and functional parameters." (PMID 39787988, 2025). "Sarcopenia diagnosis was based on Asian-specific criteria, and serum apelin concentrations were determined using enzyme immunoassay techniques." (PMID 39787988, 2025). "Apelin has garnered significant attention not only as a potential therapeutic target for sarcopenia due to its mechanistic properties but also as a candidate biomarker, given its measurable presence in blood as a secreted factor." (PMID 39787988, 2025). "Conversely, apelin administration has been shown to enhance muscle strength and physical activity in older mice, effectively reversing age-related sarcopenia and restoring youthful behavioral patterns and circadian rhythms." (PMID 39787988, 2025). "Exercise-induced apelin enhances skeletal muscle function and alleviates sarcopenia, which makes apelin a potential target for the treatment of myofibrillar atrophy, muscle weakness, and oxidative stress in aging mice." (PMID 40801027, 2025). "In recent years, apelin has emerged as a promising therapeutic agent for attenuating sarcopenia, with multiple mechanisms of action identified in cellular and animal studies." (PMID 39787988, 2025). "In summary, apelin is an exercise-responsive molecule studied in both animals and humans, but its clinical applicability in sarcopenia remains under investigation." (PMID 41441428, 2025). "Apelin seems to be involved in ameliorating sarcopenia by enhancing satellite cell function, at least in an aging rodent model, and producing an anti-inflammatory effect." (PMID 40757590, 2024). "With aging, apelin production declines, which contributes to age-related sarcopenia, and which can be reversed in aged mice by administration of the apelin peptide." (PMID 38791164, 2024). "Apelin supplementation during aging reversed sarcopenia and enhanced muscle function by triggering mitochondriogenesis, autophagy, and anti-inflammatory pathways in myofibers as well as enhancing muscle regeneration by targeting muscle stem cells." (PMID 37175901, 2023). "Among the several therapeutic interventions for CKD‐induced sarcopenia proposed over the last few decades, the apelin–apelin receptor (Apj) system has attracted some attention in recent years." (PMID 36562292, 2023). "In people with sarcopenia, the level of apelin and the synthesis of apelin in skeletal muscle decreases significantly with age and is associated with decreased strength." (PMID 35250869, 2022). "Our study highlights that P3NP, HtrA, and apelin are useful for diagnosis of sarcopenia in the clinical setting." (PMID 33743591, 2021). "A previous study have reported several biomarkers such as high temperature requirement serine protease A1 (HtrA1), procollagen III N-terminal peptide (P3NP), apelin, and heat shock protein 70 (Hsp72) are possibly involved in different components of sarcopenia." (PMID 33743591, 2021). "Apelin plays an important role in the sarcopenia of aging and positively regulates inter-myofibrillar mitochondrial content in mice." (PMID 32755574, 2020). "This supports evidence of apelin inducing more general beneficial effects on other aging organs, muscles in particular, as recently shown for sarcopenia, markers of which end up via the glomerular filtration in urine." (PMID 31337837, 2019). "Apelin may serve not only as a novel tool for the early diagnosis of sarcopenia but also as a prognostic marker for evaluating the benefits of exercise in older adults." (PMID 40801027, 2025). "Various isoforms, including apelin-13, apelin-17, and apelin-36, are likely present in biological fluids such as blood and may play distinct roles in muscle physiology and sarcopenia." (PMID 39787988, 2025). "In both apelin global knockout and muscle-specific knockout mice, sarcopenia occurs." (PMID 39590824, 2024).
sarcopenia (continued). "However, it has been reported that exercise increases the expression of apelin blood, but the findings regarding the efficacy of exercise‐induced apelin on sarcopenia are controversial and further studies are needed." (PMID 36562292, 2023). "Thus, in the development of new drugs against CKD‐induced sarcopenia, targeting the apelin–Apj system provides a promising therapeutic strategy." (PMID 36562292, 2023). "For this reason, in the elderly, apelin has been suggested as a primary marker of sarcopenia." (PMID 35250869, 2022). "We speculated that the relationship between apelin and sarcopenia might be the interaction after menopause." (PMID 33743591, 2021). "Since apelin also has kidney-protective effects, apelin might have the promising potential to act as a CKD drug that protects from kidney injury as well as CKD-associated pathologies, such as sarcopenia." (PMID 38791164, 2024). "However, we believe that apelin is a promising therapeutic target for CKD‐induced sarcopenia." (PMID 36562292, 2023). "Apelin stimulates mitochondrial biogenesis and protein synthesis by activating AMPK, AKT, and P70S6K in individuals with sarcopenia." (PMID 35250869, 2022). "On the other hand, an augmented level of apelin improves muscle function as it acts in an anti-inflammatory way and increases the regenerative abilities of muscles, which indicates that apelin may be a biomarker of early sarcopenia and even a possible treatment in this disease." (PMID 36362238, 2022). "One study showed that apelin secreted by fat cells also regulates bone turnover and lowers BMD, increasing catabolism and leading to sarcopenia." (PMID 36034420, 2022). "As a result, current evidence does not support the conclusive use of circulating apelin as a biomarker for sarcopenia." (PMID 39787988, 2025). "Consequently, despite apelin's favorable effects on muscle observed in experimental studies, our research does not substantiate the utility of blood apelin concentration as a biomarker for sarcopenia in adults aged 65 years and older." (PMID 39787988, 2025). "Additionally, stratification of participants into quartiles based on serum apelin concentrations revealed no significant variations in sarcopenia-related parameters across groups (P = 0.197 to 0.592)." (PMID 39787988, 2025). "Our data indicate that although apelin may remain a potential therapeutic target for sarcopenia, circulating apelin levels may not serve as an optimal biomarker for reflecting muscle health in humans." (PMID 39787988, 2025).
breast carcinoma (30 papers, 2014 to 2025). "In postmenopausal patients with breast cancer, an increase in level of serum apelin-36 was detected and was positively associated with BMI." (PMID 33912466, 2021). "We confirmed that high levels of Apelin expression in tumors are significantly associated with poor prognosis in breast cancer patients (Fig EV1A)." (PMID 31267692, 2019). "However, high plasma levels of apelin have also been correlated in human models in lung, colon, gastroesophageal, hepatocellular, and breast cancer, among others, increasing the risk of developing this type of pathology." (PMID 37238961, 2023). "Moreover, recent results obtained in a mouse model of breast cancer showed that loss-of-APLN markedly reduced tumor angiogenesis leading to impaired tumor growth and, consequently, improved survival of these animals." (PMID 32545380, 2020). "Importantly, loss of Apelin expression also significantly decreased microvessel densities in both E0771 and NeuT‐driven mammary tumors, as well as KRasG12D‐driven lung tumors." (PMID 31267692, 2019). "Elevated APLN levels correlate with aggressive tumor behavior and adverse prognosis in endometrial and breast cancers." (PMID 41145436, 2025). "Downregulated DEGs were significantly enriched in KEGG pathways including FoxO signaling pathway, apoptosis, Apelin signaling pathway, breast cancer, and MicroRNAs in cancer." (PMID 40805064, 2025). "For instance, APLN enhances breast cancer cells proliferation and invasion, sustains vascularization in glioblastoma (GBM), and correlates with vascular invasion in bladder cancer." (PMID 41145436, 2025). "By performing gene expression analysis of dermolipectomies from women who developed secondary LD after breast cancer, we identified a significant decrease in APLN expression in LD." (PMID 38177539, 2024). "The identification of apelin as a potential prognostic factor suggests its utility as a novel therapeutic target in breast cancer." (PMID 38255203, 2024). "In breast cancer, increased apelin levels were found to be an independent predictor of HER-2/neu expression and breast cancer phenotype, which accounts for 30% of breast carcinomas and is associated with a more aggressive tumor behavior." (PMID 36902176, 2023). "Apelin-13 induces breast cancer cell proliferation and invasion through the ERK1/2/AIB1 signaling pathway." (PMID 36632453, 2023). "According to breast cancer, several immunohistochemical studies have reported higher levels of apelin in this type of pathology." (PMID 37238961, 2023). "High apelin immunohistochemical expression has been demonstrated in breast cancer and was correlated with clinicopathological factors such as tumor size, stage, histological type, lymph node status, survival, and reduced neoadjuvant chemotherapy response." (PMID 36077676, 2022). "After this finding, several studies in cancer patients, tumor biopsies and cell lines, reported elevated levels of apelin in circulation at the protein level and at the mRNA level, especially in lung, colon, gastroesophageal, hepatocellular, and breast cancer." (PMID 36291097, 2022). "When examining patients with early stage hormone receptor-positive breast cancer, serum apelin levels and the BMI were higher in patients with breast cancer compared to the age and BMI-matched healthy control group (p = 0.0001)." (PMID 36230579, 2022). "Adipokines overexpressed in TNBC include leptin, resistin, NSMPT, LCN2, and apelin, whereas adiponectin and chemerin are significantly downregulated and their protective role against breast cancer has been suggested." (PMID 36077676, 2022). "In MCF-7 breast cancer cells, apelin initiated cell growth and invasion along the ERK1/2 pathway, and activated tumor angiogenesis." (PMID 36077676, 2022). "In a mouse implantation model for mammary carcinoma, the complete loss of APLN expression from tumor cells (by APLN-KD) and the TME (using APLN-KO) led to a decrease in tumor vessel density and tumor volumes." (PMID 34359800, 2021).
breast carcinoma (continued). "Combining Apelin inhibition (genetically or using an inactive Apelin agonist) with anti‐angiogenic therapy using different small molecular weight kinase inhibitors (sunitinib, axitinib) led to marked delay in breast cancer growth in mice." (PMID 31318171, 2019). "Nonetheless, it appears that Apelin is an ubiquitously used angiogenic pathway throughout many different types of cancers, i.e., glioblastoma, lung, and breast cancer." (PMID 31267692, 2019). "To study the contribution to tumor growth of Apelin from cancer cells or cells of the tumor microenvironment, we used the E0771 mammary cancer model and, first, specifically downregulated the expression of Apln in cancer cells using shRNA (Fig EV2B)." (PMID 31267692, 2019). "Rather, Apelin inhibition not only reduces tumor growth in our mammary tumor models, but also reduces the occurrence of anti‐angiogenic therapy‐induced metastases." (PMID 31267692, 2019). "In postmenopausal breast cancer patients, the serum apelin-36 level was increased compared to the control group and was positively correlated with BMI." (PMID 29875677, 2018). "In obese women with endometrial and breast cancer, the level of apelin-36 is also increased and positively correlated with BMI, fasting insulin levels, metabolic changes in fat tissues, hyper-inflammation, and neovascularization." (PMID 29875677, 2018). "Earlier studies have also provided evidence for apelin expression in human glioblastoma and breast cancer." (PMID 24962866, 2014). "The Apelin pathway is not well-documented in breast cancer, with only one report associating high levels of Apelin with postmenopausal breast cancer." (PMID 38565950, 2024). "Within-group comparison in breast cancer patients between the increased and the decreased apelin groups indicated that decreased apelin group had significantly increased waist and hip ratios (p = 0.008) and increased fat mass (p = 0.047) than the counterpart at the 12-month follow-up." (PMID 36230579, 2022). "Additionally, immunohistochemical staining confirmed APLN expression in cytoplasm of glioma cells, which was consistent with the distribution of APLN in colon adenocarcinomas and breast carcinoma." (PMID 36193059, 2022). "In MCF-7 breast cancer cells, apelin-13 induces the transcription of the hormone-dependent breast cancer amplified 1 (AIB1), which promotes the activation of ERK, favoring the expression of cyclin D1 and the secretion of MMP-1, leading to an increase in cell proliferation and invasion." (PMID 36291097, 2022). "In postmenopausal breast cancer (BC) patients, high levels of apelin was observed." (PMID 33912466, 2021). "Apelin blockage inhibited tumor growth and normalized blood vessels by reduced capillary leakage and tissue hypoxia and maintained pericyte coverage in vivo in mammary and breast cancer mouse models." (PMID 33707612, 2021). "We used WGCNA approach to reveal a gene network that regulate HER2-negative breast cancer treatment with taxane-anthracycline neoadjuvant chemotherapy, which enriched in pathways of estrogen signaling, apelin signaling, cAMP signaling, the PPAR signaling pathway and fatty acid metabolism." (PMID 31534839, 2019). "To complement our studies in mice, we investigated whether Apelin levels correlate with the metastatic status of women with breast cancer." (PMID 31267692, 2019). "In summary, we used WGCNA to suggest a gene network that regulate HER2-negative breast cancer treatment with taxane-anthracycline neoadjuvant chemotherapy, which enriched in pathways of estrogen signaling, apelin signaling, cAMP signaling, the PPAR signaling pathway and fatty acid metabolism." (PMID 31534839, 2019). "Next, we determined whether Apelin blockage is a suitable strategy to ameliorate cancer progression by ablating its expression in mammary cancer." (PMID 31267692, 2019).